IL6 (interleukin 6)
Diseases named in the same sentence as IL6 in open-access papers (continued):
Sharing a sentence is not in itself a finding about the gene and the disease.
Down syndrome (12 papers, 2010 to 2025). "NT-proBNP and IL-6 levels were similar between the Down syndrome with PH group and the non-Down syndrome PH group." (PMID 41239459, 2025). "In Down syndrome, increased interleukin-6 and SOD1; in Fragile X syndrome, elevated FMR1 mRNA and cytokine changes; and in Rett syndrome, increased ammonium and metabolic profile disturbances are observed." (PMID 41465426, 2025). "Furthermore, these ages related differences in serum levels of BDNF, IL-6 and MCP-1 are not statistically significative in control subjects, while in Down's syndrome patients are much more evident and statistically significative." (PMID 20181009, 2010).
dysplasia (12 papers, 2013 to 2025). A usually neoplastic transformation of the cell, associated with altered architectural tissue patterns. "Although overexpression of wild‐type LMNA elicited some increase in IL6 levels, much more significant enhancement of IL6 secretion was induced by progerin as well as by Mandibuloacral Dysplasia‐linked R527H‐mutated lamin A." (PMID 33393189, 2021). "The mean salivary IL-6 levels in mild dysplasia were 15.66 pg/ml, in moderate dysplasia were 21.433 pg/ml, and in severe dysplasia were 27.20 pg/ml." (PMID 38803729, 2024). "In serum, the mean IL-6 levels in mild dysplasia were 6.48 pg/ml, in moderate dysplasia were 17.86 pg/ml, and in severe dysplasia were 36.62 pg/ml." (PMID 38803729, 2024). "A mixed model analysis of biomarker changes revealed significantly higher IL-6 values at the end of the study in subjects with a high baseline dysplasia grade (p = 0.02 adjusted for baseline, BMI, and treatment arms)." (PMID 37764678, 2023). "Claudin-2 expression level can be increased by the activation of IL-6, and increased claudin-2 level enhances IBD-associated dysplasia and sporadic adenomas." (PMID 35865942, 2022). "Pro-inflammatory cytokines were expressed by colorectal M1 macrophages during inflammatory hyperplasia (IL-1β, IL-6) and dysplasia (IL-12, TNF-α), thus indicating that MI macrophages have a positive role during the process of carcinoma." (PMID 25434400, 2015). "Persistent exposure to inflammatory cytokines—such as IL-6, IL-8, and TNF-α—can induce urothelial hyperplasia, metaplasia, and eventually dysplasia, thereby contributing to recurrence." (PMID 41375065, 2025). "The findings demonstrated a rise in mean salivary and serum IL-6 levels across different stages of OSCC, from WDSCC to PDSCC, as well as across different grades of OED, from mild dysplasia to severe dysplasia." (PMID 38803729, 2024). "When looking at different grades of OED, a similar pattern was observed, especially for IL6 and IL8, where the biomarkers progressively increased from healthy, mild dysplasia, moderate dysplasia, and severe dysplasia, with the highest levels observed in OSCC." (PMID 36900301, 2023). "Specifically, IL-6 expression was detected in 3/11 (27.3%) of the epithelial hyperplasia cases, 10/18 (55.6%) of the dysplasia cases and 2/7 (28.6%) of the OSCC cases, whereas no positive case was detected in normal oral mucosa." (PMID 26595830, 2016). "There was also significant increase in salivary concentrations of IL-6, IL-8 and TNF-α in patients with OSCC as compared to patients with OPMDs without dysplasia." (PMID 32245251, 2020). "The results of the present study did not reveal significant differences in salivary concentration of IL-1α, IL-6, IL-8, and TNF-α between patients with OPMDs without dysplasia and healthy individuals." (PMID 32245251, 2020).
Gaucher disease (12 papers, 2012 to 2025). Gaucher disease (GD) is a lysosomal storage disorder encompassing three main forms (types 1, 2 and 3), a fetal form and a variant with cardiac involvement (Gaucher disease - ophthalmoplegia - cardiovascular calcification or Gaucher-like disease). "Elevated IL-6 levels were also reported in LSDs, including patients with Gaucher disease (associated with the expansion of myeloid cells) and those MPS IVA patients undergoing ERT (combined with induced pro-oxidant states)." (PMID 36794069, 2023). "Additionally, it appears that an IL-6 174G→Cpromoter polymorphism (of GIC genotype) is linked to a milder Gaucher’s disease phenotype, and therefore, it could play a mitigating genetic-modifying role." (PMID 37887404, 2023). "Although ectopic dsDNA dots were increased in the fibroblasts derived from PD or Gaucher’s disease patients, the amount of IL6 mRNA was comparable among control, PD, and Gaucher’s disease group." (PMID 34035300, 2021). "In a further review of the literature, there have been theories that macrophages in Gaucher disease trigger B-lymphocyte immunoglobulin secretion via IL1/IL-6 secretion." (PMID 30906609, 2019). "Human fibroblasts established from Gaucher’s disease patients harboring homozygous L444P were employed to assess effects of Gaucher’s disease on p38 activation and IL-6 formation." (PMID 26312487, 2015). "In fact, previous studies showed that GBA1 knockdown potentiates p38-dependent formation of IL-6 in human cell lines, and IL-6 has been shown to increase in serum of patients with Gaucher’s disease." (PMID 26312487, 2015). "Consistent with potentiated activation of p38, IL-6 formation was also facilitated in mouse Gaucher’s disease fibroblasts." (PMID 26312487, 2015). "In mouse Gaucher’s disease cells, p38 activation and IL-6 formation by TNF-α treatment were enhanced as compared to those of wild type." (PMID 26312487, 2015). "In Gaucher’s disease patients, however, IL-6 concentrations were increased significantly." (PMID 37887404, 2023). "Elevated IL6 (pro-inflammatory cytokine) production due to activated microglia has been observed in lysosomal storage disorders, e.g., in the brains of the Gaucher disease mouse model, in the serum of Gaucher, Fabry, and mucopolysaccharidosis type IVA patients." (PMID 32951593, 2020). "We determined serum IL-6 in Gaucher’s disease model mice using an ELISA system." (PMID 26312487, 2015). "Furthermore, human fibroblasts from Gaucher’s disease patients also displayed increases in p38 activation and IL-6 formation as comparison to healthy counterpart." (PMID 26312487, 2015). "In addition, all type of Gaucher’s disease mice also showed increases in serum IL-6." (PMID 26312487, 2015). "Neuronopathic Gaucher’s disease mouse model (GBA1V394L/V394L, saposin C-/-) has been also generated, displaying shortened life span and brain proinflammation involving elevations in active p38, IL-6 and TNF-α mRNAs." (PMID 26312487, 2015). "The pathways of IL1b and IL6 may require additional or specific stimuli (e.g., acute damage or inflammasome activation) that are not always present in Gaucher disease, especially in the early stages." (PMID 39902270, 2025). "Importantly, Gaucher’s disease patients have been reported to display elevated serum concentrations of hematopoietic growth factors and proinflammatory cytokines, including monocyte/macrophage colony-stimulating factor, TNF-α, interleukin (IL)-1β, IL-8, and IL-6." (PMID 26312487, 2015). "Among them, IL-6 and TNF-α can give rise to mature osteoclasts in the absence of RANKL and have been shown to be upregulated in Gaucher disease models." (PMID 28098793, 2017).
hemorrhagic stroke (12 papers, 2010 to 2026). A stroke caused by a bleed on the brain. "NT-proBNP and IL-6 were associated with both ischemic and the composite of ischemic and hemorrhagic stroke, and NT-proBNP was among the most important risk indicators." (PMID 40744929, 2025). "High levels of IL-6 in the acute phase of hemorrhagic stroke correlated with the severity of the cerebral edema and indicated a poor neurological outcome." (PMID 31701356, 2020). "In contrast to these influences of IL-6 in the CSF, elevated serum IL-6 has been shown to correlate with multi-organ failure and death following TBI, and is associated with poor neurological outcome following hemorrhagic stroke." (PMID 20222971, 2010). "Additionally, IL-6 and IL-10 levels were higher in hemorrhage stroke patients with 1-month unfavorable outcomes." (PMID 36439158, 2022). "In the acute phase of hemorrhagic stroke, activated microglia contribute to the clearance of cellular debris and secrete pro‐inflammatory cytokines such as TNF‐α, IL‐1β, and IL‐6, which can exacerbate neuronal injury if persistently elevated." (PMID 41363028, 2025). "The levels of Il-6, IL-8 and TNF-α were increased in all cases of ischemic and hemorrhagic stroke that were tested." (PMID 35239818, 2022). "Traditionally, pro-inflammatory cytokines, such as IL-6 and TNF-α as well as IL-1β and matrix metalloproteinases (MMPs), have been studied in a wide range of medical conditions including ischemic and hemorrhagic stroke as a surrogate for predicting poor outcomes." (PMID 35927663, 2022).
Hypocalcemia (12 papers, 2016 to 2025). An abnormally decreased calcium concentration in the blood. "The nuclear factor of activated T-cells (NFAT), which is calcium-dependent and critical for IL-6 regulation, remained stable and lower in the hypocalcemia group, indicating disrupted calcium-dependent signaling pathways." (PMID 40284849, 2025). "IL‐1 and IL‐6 activation of parathyroid and renal CaSR results in hypocalcemia, hypovitaminosis D, and hypoparathyroidism." (PMID 35894711, 2022). "The results of Th1/Th2 cytokines in peripheral blood showed that the levels of serum IL-2, IL-10, IL-6 and IFN-γ in SLE patients with hypocalcemia were significantly increased." (PMID 35757710, 2022). "In conditions such as sepsis or endotoxemia, systemic elevations of cytokines (e.g., IL-1, IL-6) diminish PTH synthesis and impair active vitamin D production, collectively resulting in functional hypocalcemia that extends beyond mere insufficient dietary intake." (PMID 40284849, 2025). "However, if low-level endotoxin exposure persists and drives a chronic inflammatory state, the inflammatory cytokines (such as IL-1 and IL-6) can suppress PTH secretion and disturb vitamin D metabolism, thereby perpetuating a cycle of hypocalcemia." (PMID 40284849, 2025). "Although administering a calcium bolus may temporarily normalize plasma calcium, cytokines such as IL-1 and IL-6 can sustain a cycle of suppressed PTH and disrupted vitamin D metabolism, thus perpetuating hypocalcemia." (PMID 40284849, 2025).
hypovitaminosis D (12 papers, 2013 to 2025). "Τhis is the first report of a physiological association of leptin and IL-6 under Athonian fasting conditions and sufficient vitamin D status, which has been reported to affect the interplay of adipokines, particularly in the existence of hypovitaminosis D, which is very common in these populations." (PMID 40218903, 2025). "Hypovitaminosis D was associated with high inflammatory activity (SLEDAI, ESR, CRP, IL-6), severity of organ damage (DI), cumulative dose of GCs, BTMs (OC, CTX) and BMD." (PMID 37558268, 2023). "Hypovitaminosis D is quite common in patients with SLE and is associated with high inflammatory activity (SLE Disease Activity Index, ESR, CRP, IL-6), severity of organ damage (Damage Index), cumulative dose of glucocorticoids, BTM changes (decrease in OC, increase in CTX) and BMD decline." (PMID 37558268, 2023). "HTLV-infected patients with hypovitaminosis D had significantly higher levels of IL-6 (95 pg/mL; IQR: 36–119) and TNF-α (50 pg/mL; IQR: 24.3–94.2) than patients with normal vitamin D levels (IL-6: 57 pg/mL; IQR: 31.4–99; p < 0.001; TNF-α: 40.3 pg/mL, IQR: 6.8–62.8; p = 0.001)." (PMID 34835029, 2021).
inflammatory bone diseases (12 papers, 2018 to 2025). "Cytokine profiling showed that crude venom and HMM suppressed osteoclastogenic cytokines such as IL-1β and IL-6, supporting their potential use in inflammatory bone diseases." (PMID 40711169, 2025). "GV infection caused osteitis, leading to a notable increase in the expression of RANK, RANKL, TNF-α, IL-6, TRAP, and MMP-2 in the femur, accompanied by an increase in the number of TRAP+, TNF-α+, and RANK+ cells, while osteoprotegerin expression decreased." (PMID 40284791, 2025). "The JAK2/STAT3 signal transduction pathway is one of the main pathways through which IL-6 exerts its biological roles and plays a critical part in inflammatory bone disease." (PMID 36643585, 2023). "It is reported that dysregulation of LEPROT is associated with various bone inflammation diseases through key cytokines, such as tumor necrosis factor alpha (TNF-α) and interleukin 6 (IL-6)." (PMID 34804118, 2021). "Osteitis induced significantly higher IL-6, cfDNA- and PMN-levels in the lavage samples (on day 7 and 14, each p < 0.05)." (PMID 29377928, 2018). "Like many chronic inflammatory states in the bone microenvironment, TLR4 activation plays a crucial role in producing various pro-inflammatory cytokines such as TNF-α, IL-6, and IL-1β in macrophages, which stimulate OC formation and contribute to the pathology of inflammatory bone diseases." (PMID 37596575, 2023). "A local infection induced a significant inflammatory response with an increase of local PMNs, NETs and IL-6 on day 7 and 14 (osteotomy vs. osteitis and osteotomy / HBO vs. osteitis / HBO), respectively." (PMID 29377928, 2018). "We also observed that vaginal infection with GV results in elevated levels of TNF-α, IL-6, and RANKL, as well as an elevated number of NF-κB-positive cells in the vagina, femur, hippocampus, and hypothalamus, leading to vaginitis, osteitis, and neuroinflammation, as previously reported." (PMID 40284791, 2025). "However, in an inflammatory microenvironment, IL-6 is highly expressed by macrophages and potentially triggers STAT3 serine phosphorylation as well as its mitochondrial translocation making it an interesting future target for therapy of inflammatory bone diseases." (PMID 36699722, 2022). "Higher expression levels of inflammatory cytokines, such as IL-6, IL-11, and TNF-α, were identified more in the bone tissue obtained from CRS patients with osteitis than in those without osteitis." (PMID 33477617, 2021).
inflammatory breast carcinoma (12 papers, 2016 to 2025). An advanced, invasive breast adenocarcinoma characterized by the presence of distinct changes in the overlying skin. "CK2 has been shown to enhance IL-6 expression in inflammatory breast cancer and has been previously implicated to be involved in Twist mediated EMT." (PMID 36009534, 2022). "A previous study demonstrated that in inflammatory breast cancer, decreasing NF-κβ significantly suppresses the expressions of IL-1β and IL-6." (PMID 40035822, 2025). "A main characteristic of inflammatory breast cancer is the secretion of proinflammatory cytokines such as IL-6 or IL-8 by macrophages, regulating angiogenesis and promoting tumor progression." (PMID 30103404, 2018). "IL-6 is produced and secreted in inflammatory breast cancer." (PMID 36979654, 2023). "In addition, reports have shown that the expression of IL-6 can be regulated by CK2 in inflammatory breast cancer, and IL-6 is an indicator of a poor prognosis." (PMID 36530985, 2022). "This study provides novel mechanistic insights into the capacity of the inflammatory cytokine IL-6 and its associated STAT3-dependent signaling pathway to stimulate proliferation in trans between individual sub-clones in a model of heterogeneity in inflammatory breast cancer." (PMID 35565421, 2022). "In inflammatory breast cancer (IBC), simvastatin blocks the activation of mesenchymal stem cells by decreasing IL-6 production." (PMID 34303383, 2021). "Most importantly, the outcome of a Phase I clinical trial indicated that a patient with inflammatory breast cancer treated with CX-4945, a potent and selective inhibitor of CK2, displayed substantially reduced levels of plasma IL-6." (PMID 33027921, 2020).
intrauterine growth restriction (12 papers, 2017 to 2025). "A significant interaction effect of intrauterine growth restriction and treatment on IL-1β (P = 0.002) and IL-6 (P = 0.02) production was confirmed by two-way ANOVA, indicating that these factors acted dependently." (PMID 30116155, 2018). "IL-6 is also greater in women who develop pre-eclampsia and fetal growth restriction, and prior work has reported that increased levels of maternal IL-6 could alter fetal neurodevelopment." (PMID 38671859, 2024). "In addition, the protein expression of leptin, VEGFA, IL-6 was increased and negatively correlated to mTORC2 signaling in human placentas collected from pregnancies complicated by intrauterine growth restriction (IUGR)." (PMID 34805133, 2021).
invasive breast carcinoma (12 papers, 1999 to 2025). A carcinoma that infiltrates the breast parenchyma. "High tumor tissue expression of OSM (p < 0.001) and IL-6 (p < 0.001) each independently correlated with a significant decrease in invasive breast cancer patient survival." (PMID 31007849, 2019). "However, anther investigation involving 55 female patients with invasive breast cancer demonstrated that the individuals with IL-6 ≥10.0 pg/ml had poorer overall survival compared with those with IL-6 <10.0 pg/ml." (PMID 35924148, 2022). "In addition, IL-6 activates MDSCs through the STAT3-NF-κB-IDO pathway in invasive breast cancer." (PMID 36249057, 2022). "Consistent with our findings there is a significant correlation between IL-6 and TGM2 mRNA expression across the 1084 patient samples in the TCGA invasive breast cancer dataset." (PMID 35729402, 2022). "Our results suggest that paracrine IL-6 signaling between preinvasive DCIS cells and stromal CAFs represent an important factor in the initiation of DCIS progression to invasive breast carcinoma." (PMID 26268945, 2015). "A recent study showed that the IL-6 signaling between human breast DCIS cells (DCIS.com and SUM102) and stromal fibroblasts represents an important factor in the initiation of DCIS cell progression to invasive breast carcinoma." (PMID 30134951, 2018).
iron overload (12 papers, 2008 to 2025). "Evidence in mouse-models and in-vitro studies suggest that hepcidin, modulated by infection/inflammation (via cytokines such as IL-6), may lead to iron overload in the respiratory tract." (PMID 28403845, 2017). "Il-1 and IL-6 regulate hepcidin transcription in mouse models and human iron overload results in increased urinary excretion of hepatocyte-produced hepcidin though the mechanism of iron sensing and the cell involved remains unclear." (PMID 18461143, 2008). "CUR and antioxidant NAC treatment decreased the level of IL-6, TNF-α, and TRACP-5b, and enhanced the level of OCN in serum of iron-overload mice." (PMID 31949885, 2019). "In dialysis children and adolescents with iron overload, ferritin levels showed a positive correlation with CRP, IL-6 and LVM." (PMID 30150549, 2018). "Second, lack of inflammatory markers (CRP, IL-6) prevents distinguishing ferritin elevation from inflammation versus true iron overload." (PMID 41470856, 2025). "In the light of increased IL-6 levels, ferritin levels become difficult to interpret, but are more suggestive of chronic inflammation rather than iron overload and, to a certain extent, surrogate markers of MetS." (PMID 34065056, 2021). "In addition, in dialysis children and adolescents with iron overload, ferritin levels showed a positive correlation with inflammation markers (CRP and IL-6) and left ventricular mass (LVM)." (PMID 30150549, 2018). "Regarding inflammation, as revealed by IL-6 and leukocyte concentrations, it was increased in patients with SCD, with and without iron overload, when compared to individuals in the control group." (PMID 29673144, 2018).